TCF21 (transcription factor 21)
Diseases named in the same sentence as TCF21 in open-access papers (continued):
Sharing a sentence is not in itself a finding about the gene and the disease.
atherosclerosis (16 papers, 2014 to 2024). A disease characterized by the build-up of fatty material and calcium deposition in the arterial wall resulting in partial or complete occlusion of the arterial lumen. "Given the role of AHR in mediating inflammation and atherosclerosis, we postulated that TCF21 may alter the risk of atherosclerosis by modulating the AHR pathway." (PMID 28481916, 2017). "For instance, SMCs differentiate into fibroblasts, contributing to the progression of atherosclerosis, where transcription factor 21 (TCF21) plays an important role in this process." (PMID 37163428, 2023). "In regard to atherosclerosis, TCF21 is induced early during atherosclerosis development to suppress SMAD3-mediated gene expression and allow SMCs to switch to a fibromyocyte phenotype." (PMID 37325472, 2023). "On the one hand, TCF21 suppresses the progression of atherosclerosis by regulating the transition from SMC to fibromyocytes and promoting the formation of antiatherosclerotic fibrous caps on the lesions." (PMID 36345357, 2022). "While TCF21 seems to reduce atherosclerosis severity by promoting the fibroblast-like vSMC, DKK3 promotes protective atherosclerotic plaque stabilization by increasing the number of contractile vSMCs." (PMID 34470477, 2021). "Transcription factor 21 (TCF21) is highly expressed within atherosclerosis lesions and coincides with SMC markers." (PMID 32630148, 2020). "Consistent with findings in atherosclerosis, the involvement of TCF21 in fibrosis has been reported in a number of other organs." (PMID 32630148, 2020). "In order to explore the functional role of miR-30-5p/TCF21 axis in atherosclerosis, five groups of the cell model were conducted: normal, blank, siNC, siTGF21, ox-LDL-treated THP-1 cells transfected with TCF21 siRNA and miR-30-5p inhibitor (siTCF21+inhibitor)." (PMID 31354385, 2019). "qRT-PCR, Western blot, ELISA, CCK8, and flow cytometry assays showed that the inhibitory activity of miR-30-5p against the atherosclerosis progression was achieved by regulating the TCF21-targeting NF-κB and MAPK signal pathways." (PMID 31354385, 2019). "The present study is aimed not only at investigating the effects of miR-30-5p on the progression of atherosclerosis in vitro but also at investigating the mechanisms that connected miR-30-5p/TCF21 and atherosclerosis." (PMID 31354385, 2019). "Our results reveal that miR-30-5p suppresses the progression of atherosclerosis through targeting TCF21 in vitro." (PMID 31354385, 2019). "AHR ligand-induced atherosclerosis has been linked to altered AHR-regulated redox-pro-inflammatory events and interactions with the transcription factor TCF21, which plays an important role in atherosclerosis." (PMID 30513921, 2018). "To establish a potential role of miR-224-TCF21 regulation during atherosclerosis progression, we measured endogenous levels of miR-224 and TCF21 in human coronary artery lesions." (PMID 24676100, 2014). "Lastly, miR-224 and TCF21 were localized in human coronary artery lesions and anti-correlated during atherosclerosis." (PMID 24676100, 2014). "The TCF21 gene has been associated with CAD, promoting the stability of plaques and reducing clinical events by modulating the phenotypic transition from smooth muscle cells to fibromyocytes in atherosclerosis." (PMID 38250610, 2024). "The mesenchymal-like VSMC might further shift to myofibroblast-like VSMC, which is regulated by transcription factor 21 (TCF21) and considered a protective phenotype in atherosclerosis." (PMID 38138958, 2023). "The specific effects of TCF21 on atherosclerosis are complex." (PMID 36345357, 2022). "This suggests that TCF21 might promote atherosclerosis via increasing the apoptosis rate and ROS accumulation." (PMID 36345357, 2022). "Together, these studies suggest that TCF21 is an important player in atherosclerosis-related fibrosis and might modulate plaque stability via fibrous cup support." (PMID 32630148, 2020).
atherosclerosis (continued). "Moreover, NF-κB and MAPK signal pathways involved in the regulation of miR-30-5p/TCF21 axis on atherosclerosis were detected by Western blot." (PMID 31354385, 2019). "In addition, GO terms enrichment and PCA analysis performed using goseq yielded multiple immune system and atherosclerosis- related GO terms, implicating TCF21 in HCASMC to promote immune and pro-atherosclerotic-responses." (PMID 28481916, 2017). "By identifying genes that are regulated by TCF21 we have been able to link together multiple other CAD associated genes and begin to identify the critical molecular processes that mediate atherosclerosis in the blood vessel wall and contribute to the genesis of ischemic cardiovascular events." (PMID 26020271, 2015). "PDGF has been extensively implicated in atherosclerosis pathogenesis, and in vitro genomic studies have suggested that TCF21 mediates PDGF signaling (, and data not shown)." (PMID 24676100, 2014). "In addition, the mir-30-5p-transcription factor 21 (TCF21)-MAPK/P38 signaling pathway might be a potential biomarker or therapeutic target of atherosclerosis." (PMID 35246136, 2022). "Therefore, the miR-30-5p-TCF21-MAPK/p38 signaling pathway may be a potential biomarker or therapeutic target in atherosclerosis." (PMID 31354385, 2019). "TCF21 encodes a basic-helix-loop-helix transcription factor that is involved in controlling cell fate decisions in developing coronary artery SMC, and may provide insight into the possible causal role of this cell type in atherosclerosis." (PMID 24676100, 2014). "In addition, research has provided potential therapeutic targets and new ideas for the treatment of atherosclerosis, including Ntn1, NOTCH, and Tcf21." (PMID 36267275, 2022). "In fact, Tcf21 SMC-specific knock-out in ApoE−/− mice inhibits VSMC phenotypic modulation and limits their presence in the fibrous cap, supporting a protective role of TCF21 in atherosclerosis." (PMID 35626694, 2022). "Meanwhile, TCF21 can directly target NF-κB and MAPK signal pathways to regulate atherosclerosis." (PMID 31354385, 2019). "In order to explore the functional role of TCF21 on atherosclerosis, we also conducted four groups of the cell model: normal, blank, ox-LDL-treated THP-1 cells transfected with siRNA negative control (siNC), and ox-LDL-treated THP-1 cells transfected with TCF21 siRNA (siTGF21)." (PMID 31354385, 2019). "Also, while leukocytes are an appropriate cell type in atherosclerosis and express a number of the signaling components upstream of TCF21, they may not be the primary cell type reflecting TCF21 function." (PMID 24676100, 2014). "However, whether miR-30-5p/TCF21 axis contributes to atherosclerosis is by far not clear." (PMID 31354385, 2019).
ovarian carcinoma (14 papers, 2010 to 2026). A malignant neoplasm originating from the surface ovarian epithelium. "Increasing miR-205 in ovarian cancer cells caused a significant reduction in TCF21 activity as measured using a luciferase reporter construct containing the miR-205 target site." (PMID 28476165, 2017). "In ovarian cancer, transcription factors such as transcription factor 21 (TCF21), cAMP response element binding protein 1 (CREB1), and suppressor of mothers against decapentaplegic homolog (SMAD2/3/4) have emerged as critical regulators of this process." (PMID 41590379, 2026). "In ovarian cancer, miR-205 directly targets TCF21, resulting in high expression of MMP-2, which increases cancer cell migration." (PMID 34721577, 2021). "In accordance with the results in our study, TCF21 was significantly downregulated in ovarian cancer tissues, and miR-205 seems to have a pivotal role in the spread of ovarian cancer through binding to TCF21." (PMID 30804710, 2019). "This is supported by our findings that miR-205 targets TCF21 and reverses TCF21-mediated decreases in ovarian cancer cells invasion." (PMID 28476165, 2017). "We used qRT-PCR to quantitate TCF21 expression in ovarian cancer tissue and ovarian cancer cell lines." (PMID 28476165, 2017). "In order to understand the impact of miR-205 on TCF21-induced inhibition of cell invasion, we co-transfected miR-205 mimic into ovarian cancer cells along with the TCF21 expression vector, and then measured invasion properties using Transwell invasion assay." (PMID 28476165, 2017). "We conclude that miR-205 regulates invasive behavior of epithelial ovarian cancer cells by targeting the tumor suppressor, TCF21." (PMID 28476165, 2017). "We demonstrated that TCF21 expression was downregulated in stage I to stage IV ovarian cancer tissue and ovarian cancer cell lines." (PMID 28476165, 2017). "TCF21 expression was significantly down-regulated in stage I to stage IV ovarian cancer tissue compared to normal ovarian tissues." (PMID 28476165, 2017). "Real time qRT-PCR and Western blot analysis confirmed that miR-205 in ovarian cancer cells down-regulated TCF21 expression." (PMID 28476165, 2017). "miR-205 mimic was co-transfected into ovarian cancer cell lines along with the TCF21 wild-type or mutant reporter vectors and internal control pRL reporter vectors." (PMID 28476165, 2017). "We identified an inverse relationship of increased miR-205 expression and decreased TCF21 expression in ovarian cancer tissue which was more prominent in the advanced stages of the disease." (PMID 28476165, 2017). "Using Western blot analysis, we found that TCF21 protein levels were significantly decreased in ovarian cancer tissue and ovarian cancer cell line OVCAR-5, OVCAR-8 and SKOV-3 compared with normal ovarian tissue." (PMID 28476165, 2017). "As expected, transfection of TCF21 expression plasmid significantly increased both TCF21 mRNA expression and protein levels in ovarian cancer cell lines." (PMID 28476165, 2017). "TCF21 expression was significantly decreased in three ovarian cancer cell lines OVCAR-5, OVCAR-8 and SKOV-3 compared to normal ovarian tissues." (PMID 28476165, 2017). "Quantitative real-time polymerase chain reaction and western blot were performed to assess miR-205 and transcription factor 21 (TCF21) expression in ovarian cancer and normal ovary samples." (PMID 28476165, 2017). "The present findings strongly support a role for TCF21 in cell invasion properties of ovarian epithelial cancers." (PMID 28476165, 2017). "It has been reported that miR-205 enhances invasion of ovarian cancer cells by inhibiting TCF21." (PMID 34690112, 2021). "TCF21 antisense RNA inducing demethylation (TARID), an antisense RNA of TCF21 that is a tumor suppressor, binds and recruits GADD45a to the TCF21 promoter to facilitate demethylation in several cancers, including non-small cell lung cancer, head and neck squamous cell carcinomas and ovarian cancers." (PMID 33435206, 2021).
ovarian carcinoma (continued). "In this investigation, we test the hypothesis that miR-205 regulates TCF21 mediated tumor suppression in ovarian cancer leading to tumor progression." (PMID 28476165, 2017). "The results provide a new understanding of miR-205 and TCF21 expression and insight into the mechanisms in ovarian cancer tumorigenesis which could lead to the development of new anticancer therapies." (PMID 28476165, 2017). "miR-205 appears to have an important role in the spread of ovarian cancer by targeting TCF21." (PMID 28476165, 2017). "However, the transfection of miR-205 mimic into ovarian cancer cells diminished TCF21-mediated inhibition of cell invasion." (PMID 28476165, 2017). "To better understand the mechanism of miR-205 and TCF21 on ovarian cancer cells invasion properties, we tested the hypothesis that MMPs were important for invasive behavior." (PMID 28476165, 2017). "The inhibition of MMPs may be one mechanism by which TCF21 decrease ovarian cancer cell invasion properties." (PMID 28476165, 2017). "We found that TCF21 alone inhibited the invasiveness of ovarian cancer cells." (PMID 28476165, 2017). "Decreased TCF21 expression levels were related to ovarian cancer stages." (PMID 28476165, 2017). "miR-205 directly targeted TCF21, which was significantly decreased in ovarian cancer tissue." (PMID 28476165, 2017). "miR-205 targets TCF21 and regulates TCF21 mediated MMP expression in ovarian cancer cell invasion." (PMID 28476165, 2017). "The MMP-2 inhibition by presence of TCF21 in ACC cells was also reported in colon rectal and ovarian cancer cells, showing the TCF21 properties in decrease cell invasion of different types of tumors through inhibition of MMP-9 and MMP-2." (PMID 35201460, 2021). "Another direct target of miR-205 is transcription factor 21 (TCF21), which is a reduced tumor suppressor in ovarian cancers." (PMID 34721577, 2021). "In the current study, we found that miR-30a-mediated DEGs are involved in the regulation of key biological processes of ovarian cancer, such as SOX9, transcription factor 21 (TCF21), Wnt-5a,etc." (PMID 33004058, 2020). "Since miR-205 inhibits transcription factor-21 (TCF-21), it increases the ability of ovarian cancer cells to spread and metastasize." (PMID 31035447, 2019). "There were significantly decreased TCF21 expression in stage III and stage IV ovarian cancer compared with stage I and II ovarian cancer." (PMID 28476165, 2017). "Co-transfection of TCF21 expression plasmid with miR-205 mimic diminished the inhibitory effect of TCF21 on MMP-2 and MMP-10 in ovarian cancer cells." (PMID 28476165, 2017). "TCF21 inhibited MMP-2 and MMP-10 and decreased ovarian cancer cell invasion." (PMID 28476165, 2017). "We overexpressed TCF21 in OVCAR-5, OVCAR-8 and SKOV-3 cells to determine whether or not TCF21 alters the invasion properties of ovarian cancer cells." (PMID 28476165, 2017).
melanoma (11 papers, 2015 to 2025). A malignant, usually aggressive tumor composed of atypical, neoplastic melanocytes. "Functionally, TCF21 binds the promoter of the melanoma metastasis-suppressing gene KISS1 and enhances its expression." (PMID 37369946, 2023). "By using quantitative DNA methylation analysis in melanoma biopsies of patients and in their derived cell lines, it was demonstrated that TCF21 expression is downregulated in metastatic melanoma by promoter hypermethylation." (PMID 33729392, 2021). "Since then, TCF21 has been studied in other types of human cancers and is considered a tumor suppressor gene in melanomas, renal cancer, adrenocortical carcinomas, colorectal tumors, gastric cancer, and hepatocellular carcinomas (18,)." (PMID 33729392, 2021). "We found that LIN28B expression was strongly decreased by TCF21 upregulation in the two melanoma cells." (PMID 34424910, 2021). "The result displayed that LIN28B expression were significantly diminished by TCF21 upregulation in the two melanoma cells." (PMID 34424910, 2021). "In a melanoma cell line (C8161), re‐expression of TCF21 was described to activate expression of the metastatic suppressor KISS1 and consequently inhibit motility of the cells." (PMID 29080283, 2018). "TCF21 expression is downregulated in metastatic melanoma by hypermethylation of a promoter, and overexpression of TCF21 inhibits the motility of melanoma cells via KISS1." (PMID 28476165, 2017). "The up-regulation of TCF21 has been found to impede the motion of melanoma cells." (PMID 38097858, 2024). "The TCF21/miR-10a-5p/LIN28B pathway could be targeted by a repressor in a new melanoma treatment in order to stop melanoma progression." (PMID 36982460, 2023). "In addition, the effect of TCF21 high expression on proliferation, invasion and migration capacity of melanoma cells was also explored." (PMID 34424910, 2021). "We further found that raised TCF21 expression could block melanoma cells’ proliferation, invasion and migration, which could be obviously reversed by decreased miR-10a-5p expression." (PMID 34424910, 2021). "Likewise, in other human cancer types, such as gastric cancer, colorectal cancer, melanoma, head and neck cancer, and non‐small‐cell lung carcinoma, hypermethylation is described to be the predominant mechanism for TCF21 downregulation." (PMID 29080283, 2018). "Besides, TCF21 inhibited melanoma cell proliferation and invasion via miR-10a-5p/LIN28B." (PMID 40226362, 2025). "Finally, overexpression of TCF21 inhibits the motility of the C8161 human melanoma cell line." (PMID 33729392, 2021). "Collectively, these results implied that TCF21/miR-10a-5p/LIN28B axis played a crucial role in the growth and invasion of melanoma." (PMID 34424910, 2021). "Functionally, TCF21 binds to the KISS1 promoter, a melanoma metastasis-suppressor gene, increasing its expression." (PMID 33729392, 2021). "Arab and coworkers found that TCF21 directly bind the promoter of KISS-1 gene, known as metastasis inhibition gene in a number of tissues, to enhance its expression in melanomas." (PMID 35201460, 2021). "The observation of the bona fide TSGs affected by promoter hypermethylation in CMM suggests that these molecules, e.g., TCF21, SOCS, RUNX, RASSF6, RASSFA, RARβ, MAPK13, H- and E-cadherin and AGTR, are a candidate for the design of new therapeutic strategies for human melanoma." (PMID 34639015, 2021). "In addition, we verified that the TCF21/miR-10a-5p/LIN28B axis played a key role in proliferation, invasion, migration in melanoma." (PMID 34424910, 2021). "Furthermore, TCF21 is downregulated in adrenocortical carcinoma (ACC), melanoma, lung, and head and neck squamous cell carcinomas." (PMID 26421305, 2015). "TCF21 induced miRNA-10a targeting LIN28B could affect the progression and growth of melanoma." (PMID 34424910, 2021).